TLR7 (toll like receptor 7)
Diseases named in the same sentence as TLR7 in open-access papers (continued):
Sharing a sentence is not in itself a finding about the gene and the disease.
tumor (continued). "In murine nonepithelial tumours, CD-40/TLR-7 agonists have been utilized as adjuvants in vaccination with exogenous tumour antigen, which resulted in stronger and less toxic antitumour memory T-cell responses compared to monotherapy." (PMID 24475147, 2014). "No previous studies have shown that the TLR7 agonist IMQ modulates glucose metabolism in tumor cells." (PMID 24658058, 2014). "Taken together, our results indicate that IMQ can enhance aerobic glycolysis in tumor cells and that this process is independent of TLR7 and TLR8 expression." (PMID 24658058, 2014). "To resolve whether the IMQ-induced aerobic glycolysis was mediated by TLR7/8, we examined TLR7 and TLR8 expression in the tumor cell lines and primary human keratinocytes." (PMID 24658058, 2014). "In this study, we demonstrated that IMQ treatment greatly enhanced aerobic glycolysis in tumor cells in a manner independent of TLR7/8 expression." (PMID 24658058, 2014). "Furthermore, it has an additional advantage over classical TLR7 or TLR9 ligands such as imiquimod, as MV induces the release of tumor antigens for cross-presentation following the lysis of infected tumor cells." (PMID 24832799, 2013). "Rats were subcutaneously (SC) injected in the flank, contralateral to the tumor-implanted side, with resiquimod (R848) (Invitrogen, TLRL-R848), a Toll-like receptor 7/8 agonist, at a dose of 100 μg/kg, corresponding to 30 μg/dose, three times per week on Mondays, Wednesdays and Fridays." (PMID 24955288, 2012). "Our findings suggest that the MDSCs recruited to the lungs starting on day 5 would recognize the presence of RNA through TLR7 and become hindered in their capacity to inhibit the ongoing inflammatory response similar to TLR9 ligand mediated inhibition of MDSC tumor suppression." (PMID 21966467, 2011). "Indeed, we have recently confirmed that Ly6AE-upregulation on CD8 T cells occurs in a strictly IFN-α/β-dependent manner after AB1-HA tumor treatment with the TLR3 and TLR7 agonists poly-I:C and imiquimod." (PMID 19746156, 2009). "IRF-5 is a key player of TLR7/TLR9 signalling and is involved in tumor cell growth and apoptosis." (PMID 19430534, 2009). "Given the evidence that IFNA subtypes differ in potency in their anti-viral and anti-tumor activities, the induction of a variety of IFNA subtypes and IFNB by TLR7 agonists may be an advantage over therapies that utilize a single IFNA subtype." (PMID 17935622, 2007). "Multiplex immunofluorescence analysis revealed that TLR7 was significantly upregulated by IFNα therapy in cells expressing myeloid cell markers such as CD1c+, CD68+ and CD141+ and in XCR1+ cells, a marker specific for type I DCs in the tumor and the surrounding stroma." (PMID 39849091, 2025). "In addition, the TLR7/8 agonist imiquimod (IMDQ) conjugated to nanobodies regulates the mannose receptor (MR) and induces M1-like repolarization of alveolar macrophages, which obviously suppresses tumor progression." (PMID 41293166, 2025). "Additionally, we encapsulated the Toll-like receptor 7/8 agonist R848 within the CCR6-modified macrophage membrane (CCR6-MM) to polarize M2-type TAMs to the M1 phenotype, reducing CCL20 secretion and transforming the immunosuppressive tumor microenvironment." (PMID 41625363, 2025). "Similarly, a HER2-targeted ADC carrying a Toll-like receptor 7 (TLR7) agonist activates innate immune responses within tumors, inducing tumor regression through immune stimulation rather than direct cytotoxicity." (PMID 41007788, 2025). "Notably, CD1a+ cells showed TLR7 expression only when they were infiltrating the tumor, but not in the stroma." (PMID 39849091, 2025). "Furthermore, combination therapy with TLR7 and TLR9 agonists 1V270 and SD-101(CpG) and immune checkpoint inhibitor (anti-PD1 mAbs) successfully induced tumor regression along with an increased ratio of M1-like to M2-like TAMs in murine models of head and neck squamous cell carcinoma." (PMID 40050933, 2025).
tumor (continued). "As dosing intervals of TLR7 agonists have been reported to be an important factor for immunostimulatory activity, we compared the effect of once weekly (q1w) DSP-0509 dosing frequency with that of biweekly (q2w) on the anti-tumor activity of the RT and DSP-0509 combination." (PMID 39054418, 2024). "In accordance, many TLRs agonists (imiquimod for TLR7 and CpG for TLR9) or cGAS-STING triggers were employed to activate anti-viral interferon-mediated immune responses with final aim to polarise myeloid cells towards an anti-tumour state, prime, and support T cell-mediated anti-tumour immunity." (PMID 36161514, 2023). "As an adaptor for TLR7-9 signaling, the TASL-SLC15A4 complex specifically activates the transcription factor IRF5, which in turn induced the release of proinflammatory cytokines, chemokines, and IFNs, the latter of which can play an integral role in tumorigenesis and tumor progression." (PMID 37296415, 2023). "Finally, combining a single dose of TransCon TLR7/8 Agonist with systemic immunotherapy enhanced tumor growth inhibition in both injected and non-injected tumors, and demonstrated immune memory in a tumor rechallenge setting." (PMID 36123697, 2022). "Upon tumor rechallenge with CT26 cells, none of these previously treated mice displayed tumor growth, demonstrating that the combination of TransCon TLR7/8 Agonist with systemic immunotherapy promoted the functional generation of a robust anti-tumor immune memory response." (PMID 36123697, 2022). "Another TLR7/8 agonist-based nanovaccine combined with sunitinib and PD-L1 antibody treatment was proven to upregulate activation of CD8+ T cells and reduce MDSCs and PD-L1high M2 macrophages in the tumor, leading to enhanced antitumor efficacy in B16F10 and MB49 mice models." (PMID 35413927, 2022). "In this study, we first developed a multifunctional nanoplatform based on mesoporous hexagonal core–shell zinc porphyrin-silica nanoparticles (MPSNs) loaded with R837 (a toll-like receptor-7 agonist), which could be used to integrate PDT, PTT, and tumor-specific immunotherapy for breast cancer." (PMID 35392911, 2022). "Indeed, IT delivery of TransCon TLR7/8 Agonist led to an increase in activated CD8 and CD4 T cells in peripheral blood and tDLN, which may contribute to systemic anti-tumor responses." (PMID 36123697, 2022). "After loading with R837 (imiquimod, a toll-like receptor-7 agonist), MPSNs@R837 will elicit high-efficiency immunogenic cell death via PDT and PTT, and promote dendritic cell maturation after the PH-responsive release of R837, thereby, inducing tumor-specific immune responses." (PMID 35392911, 2022). "Indeed, we found that B cell KO mice generated significantly milder responses to anti-PD-L1 antibody, TLR-7/8 agonist, or the combination of TLR-7/8 agonist plus anti-PD-L1 antibody than WT mice, as demonstrated by shorter survival and larger tumor size of the B cell KO mice." (PMID 35720386, 2022). "The modulation of TLR7 and TLR8 responses is independent of CpG motifs or the nature of the oligodeoxynucleotides (ODNs) backbone structure, and the crosstalk between ODNs, IRMs, and TLR7 and TLR8 may be used for different clinical implications, including tumor therapy." (PMID 36476317, 2022). "Given the observation that TransCon TLR7/8 Agonist monotherapy induced activation of both innate (NK) and adaptive (CD8+) cytolytic cell types, we hypothesized that it could also potentiate anti-tumor efficacy when combined with systemic immunotherapy." (PMID 36123697, 2022). "For instance, combining TLR7 and TLR9 agonists (1V270 and SD-101) with anti-PD1 checkpoint inhibitor activated tumor-infiltrated macrophages and induced a potent antitumor immune response, preventing primary tumor growth and metastasis in a mouse model of head and neck cancer." (PMID 34124272, 2021).
tumor (continued). "TLR4−/−, TLR7−/− and TLR9−/− untreated tumors presented significantly small volume compared to WT untreated tumors indicating that these TLRs could be involved in normal tumor development." (PMID 34341449, 2021). "Therefore, we performed an in vitro assay with TLR7/8 agonist treated tumor cell lines as additional control demonstrating no IFN-α2 release." (PMID 33013879, 2020). "In addition, several preclinical studies have demonstrated that agonists of the TLRs (TLR3, TLR7/8 and TLR9) in macrophages may enhance anti-tumor treatment efficacy by polarizing M0 macrophages into Th1 and M1-like TAMs and inhibiting tumor progression." (PMID 33323552, 2020). "Combined, these results confirm that host rather than neoplastic TLR7 is necessary for R848’s beneficial effects and substantiate caution that TLR7 activity may increase tumor burden if unchecked by immune response." (PMID 31615993, 2019). "Additionally, soluble IMQ inhibited the proliferation of GL261 cells in a TLR7-independent manner because TLR7 mRNA was not expressed in the tumor cells." (PMID 31240216, 2019). "Another agonist of TLR7 and TLR8, namely R848 or resiquimod, loaded into β-cyclodextrin nanoparticles induced a functional re-orientation of the TME, in which the M2-like TAMs shifted toward a M1-like TAM phenotype, reducing tumor growth in multiple murine tumor models." (PMID 30349530, 2018). "For future experiments, a control group without seeded tumor cells may be included, to isolate the inflammatory effect of TLR-7 activation." (PMID 29767328, 2018). "Most of the TLR7 agonists have no direct cytotoxic effects on tumor cells." (PMID 28620298, 2017). "Interestingly, we found lapatinib to work better with SZU-101, enhancing tumor clearance in vivo, without affecting the TLR7-NF-κB pathway activated by the TLR7 agonist in mouse spleen lymphocytes and bone marrow dendritic cells (BMDCs)." (PMID 28000738, 2016). "Moreover, tumor-secreted miR-21 can function via binding as ligands to murine TLR7 and human TLR8 in immune cells, thereby triggering a TLR-mediated prometastatic inflammatory response that ultimately may lead to tumor growth and metastasis." (PMID 26116372, 2015). "In this study, we demonstrated that IMQ increased glucose uptake, glucose utilization and lactate secretion and reduced mitochondria respiration, indicating that IMQ increased the rate of aerobic glycolysis, in both TLR7/8-expressing and TLR7/8-non-expressing tumor cells." (PMID 24658058, 2014). "Additionally, IFNα did not affect tumor cell proliferation in vitro, at concentrations corresponding to those induced by TLR7 activation." (PMID 24390981, 2014). "Lewis rats treated with a vaccine without immunostimulatory TLR7/8 agonist showed little inhibition of tumor growth relative to untreated control rats, while the TLR7/8 containing vaccine strongly suppressed tumor growth when given 3 times per week starting at day 10 after implantation." (PMID 24955288, 2012). "With the TLR7 agonist Imiquimod, this vaccine generated E7-specific antitumor effects and prolonged the survival in treated mice, probably by also decreasing the number of myeloid-derived suppressor cells (MDSC) in the tumor microenvironment of tumor-bearing mice." (PMID 24212964, 2011). "IRF-5, likely a tumor suppressor, is highly expressed in EBV transformed cells and, together with IRF-4, may be involved in the EBV-mediated regulation of Toll-like receptor 7 activities." (PMID 20209099, 2010). "With acquisition of functionality in FRβ restricted to the tumor microenvironment, we decided to evaluate whether a folate-targeted TLR7 agonist might be able to induce a proinflammatory phenotype in tumor myeloid cells without activating immune cells in healthy tissues." (PMID 38384467, 2024).
tumor (continued). "Tumor-secreted exosomal miR-21 and miR-29a can bind to murine TLR7 (Toll-like receptor 7) and human TLR8 (Toll-like receptor 8) in immune cells, inducing a TLR -mediated inflammatory response that may eventually provide suitable conditions for tumor metastasis." (PMID 34595207, 2021). "In addition, the involvement of HIF-1α in TLR7/8-mediated inflammatory response in THP-1 human myeloid macrophage had been reported, but whether IMQ can modulate glucose metabolism through HIF-1α in tumor cells remains unclear." (PMID 24658058, 2014). "Thus, IMQ-enhanced aerobic glycolysis may occur in TLR7/8 non-expressed tumor cells, however, the expression of TLR7 may strengthen this effect." (PMID 24658058, 2014). "More recently, we described in advanced stage pancreatic cancers overexpressed TLR2, TLR4, TLR7, and TLR9 predominantly in tumor cells rather than tumor-infiltrating immune cells, making TLR inhibition strategies in this tumor even more interesting." (PMID 38390872, 2024). "A low CD3–CD8 tumor–stroma index indicated a worse prognosis among all TLR subgroups, except the TLR7-negative subgroup." (PMID 36649244, 2023). "Surprisingly, the responses were not correlated with an increase in viral signaling proteins (RIG-I, TLR7, and TLR8), viral entry proteins (ICAM-1 and DAF), or PD-L1, nor was an inflamed tumor microenvironment found." (PMID 37569757, 2023). "Interestingly, S-FLU without NY-ESO-1 showed a partial but significant protection against tumour development in lungs, suggesting that non-specific innate immune response mediated through TLR7 by virus single-strand RNA may be utilized for anti-tumour response." (PMID 36626205, 2023). "Moreover, mice that showed complete responses following treatment with TransCon TLR7/8 Agonist and IL-2 did not develop palpable tumors following tumor rechallenge, indicating immunological memory developed with the combination treatment during the initial tumor challenge." (PMID 36123697, 2022). "Our resultswere consistent with the previous study and demonstrated low polymerbinding to CD45+ immune cells and significantly higherbinding of only PDS-containing p(Man-TLR7-PDS), but not p(Man-TLR7),to TRP1+ B16F10 tumor cells." (PMID 36313164, 2022). "While the current studies demonstrate the potential of TLR7/8 and STING agonist combination as vaccine adjuvants, we did not observe complete tumor eradication in any of the treated mice." (PMID 36551577, 2022). "In KIRC, the results suggested that the mRNA levels of TLR1, TLR2, TLR3, TLR4, TLR7, and TLR8 were elevated in tumour tissues compared with normal kidney tissues." (PMID 34531911, 2021). "Unlike in the case of TLR7/8/9 antagonism in LLC, R848 decreases tumor size in most PDAC cell lines tested." (PMID 31615993, 2019). "However, within the context of cancer, the activation response of pDCs to TLR7/9 is impaired, resulting in decreased or absent production of IFN-α, which in turn, leads to the establishment of an immunosuppressive tumor microenvironment." (PMID 38533503, 2024). "However, these pDCs are not activated, there is a lack of TLR7 and TLR9 signaling in the tumor environment, there is no production of type 1 IFN, and they have been associated with tumor growth." (PMID 33342561, 2021). "Because our functional polymer, p(Man-TLR7-PDS),could also hypotheticallybind mannose receptor or other c-type lectins on tumor cell surfaces, we verified that mannose monomer incorporation into the polymerdid not affect PDS-mediated tumor cell binding, with or without mannosepreincubation." (PMID 36313164, 2022).
infection (447 papers, 2007 to 2026). The state of being infected such as from the introduction of a foreign agent such as serum, vaccine, antigenic substance or organism. "This association is described in SARS-CoV-2 infected mice, where Tlr7 deficiency leads to higher lung viral load 6–10 days post-infection." (PMID 41445728, 2025). "Specifically, excessive activation of TLR7 has been linked to increased host-mediated lung damage during infection with ssRNA viruses including IAV, SARS-CoV-2 and RSV21–24." (PMID 40442368, 2025). "Acute infection resulted in body weight loss in both WT and TLR7 KO mice, although WT mice lost significantly more weight than TLR7 KO mice, suggesting that the infection was more severe in TLR7-expressing mice." (PMID 40442368, 2025). "In the current study, transcriptome analyses indicated that Toll-like receptor (TLR) receptors (Tlr7, Tlr8, and Tlr9) associated with type I IFNs production were significantly upregulated after infection." (PMID 40124358, 2025). "In platelets, PLAUR was positively associated with TLR2, TLR4, TLR8, and RIG-I, and with infection these associations changed to TLR7 and LGP2 but continued to correlate with TLR4 and TLR8." (PMID 40825056, 2025). "During Streptococcus pneumoniae infection, the deficiency of endosomal TLR-mediated (TLR7/9) nucleic acid sensing pathways in alveolar macrophages leads to enhanced infection." (PMID 41293166, 2025). "This is further supported by the observation that increased levels of TLR3 in platelets and TLR5 in leukocytes correlate with severity of infection and survival, while increased levels of leukocyte TLR7 are associated with reduced severity of infection." (PMID 40825056, 2025). "At the early stage of immune infection, MXSGD + SJZD can control the inflammatory damage caused by infection by inhibiting the TLR7 pathway." (PMID 39221016, 2024). "In genetically predisposed individuals, factors such as infections, endocrinological abnormality and metabolic abnormalities can cause TLR7 dysregulation, aggravating primary Sjogren’s syndrome symptoms and progression." (PMID 39736771, 2024). "In enterovirus 71 (EV71) infection, the G allele was associated with a lower risk of serious diseases related to higher TLR7 gene expression and IFN-α levels." (PMID 39650644, 2024). "We demonstrate that TLR7 is expressed on RBCs and observe increased membrane association of TLR7 during infection." (PMID 38982195, 2024). "(c) Are TLR7 expression levels associated with the capacity to maintain CD4+ T cell homeostasis during primary infection?" (PMID 37227774, 2023). "The results of the subgroup analysis demonstrated that the association between TLR7 rs179008 SNP and the infection by HCV is statistically significant in the North African population but not in the European population." (PMID 37869679, 2023). "The association between this TLR7 gene polymorphism and the infection by HCV is statistically significant." (PMID 37869679, 2023). "For this reason, we can agree that the association between this TLR7 gene polymorphism and the infection by HCV is statistically significant." (PMID 37869679, 2023). "An analysis of TLR7 polymorphisms in 381 children with AOM showed that TLR7 polymorphisms reduced the risk of rhinovirus-associated infection." (PMID 34360632, 2021). "CD4+ T cells and CD8+ T cells from both WT and TLR7 KO mice expressed higher levels of activation-associated molecules after infection for 6 weeks (P < 0.05)." (PMID 34692568, 2021). "In summary, this evidence indicated that TLR7 KO mice were susceptible to death during the acute infection stage." (PMID 34692568, 2021). "A recent study established association of allele frequencies at three TLR loci (TLR1LA, TLR2B, and TLR7) with infection of malarial parasites in songbirds." (PMID 33209285, 2020).